FGD5 (FYVE, RhoGEF and PH domain containing 5)
Description:
Activates CDC42, a member of the Ras-like family of Rho- and Rac proteins, by exchanging bound GDP for free GTP. Mediates VEGF-induced CDC42 activation. May regulate proangiogenic action of VEGF in vascular endothelial cells, including network formation, directional movement and proliferation. May play a role in regulating the actin cytoskeleton and cell shape.
Synonyms: ZFYVE23; FLJ39957; FLJ00274
Tractability: Antibody: its Gene Ontology location is reachable by antibodies, with high confidence; the Human Protein Atlas places it where antibodies can reach. PROTAC: ubiquitination databases record sites on it.
Gene: Protein-coding gene on chromosome 3 (14,810,518 to 14,934,571, forward strand). Ensembl gene ENSG00000154783.
Subcellular location: Cytoplasm, cytoskeleton; Cell projection, ruffle membrane; Endoplasmic reticulum; Golgi apparatus; Early endosome
Subcellular location (Human Protein Atlas): Plasma membrane
Pathways (Reactome):
Signal Transduction: RAC1 GTPase cycle
Gene Ontology:
Molecular function: protein binding; guanyl-nucleotide exchange factor activity; small GTPase binding; metal ion binding
Biological process: actin cytoskeleton organization; cytoskeleton organization; filopodium assembly; regulation of cell shape; regulation of GTPase activity; regulation of small GTPase mediated signal transduction
Cellular component: plasma membrane; cytoplasm; cytosol; Golgi apparatus; lamellipodium; ruffle; cytoskeleton; early endosome; endoplasmic reticulum; ruffle membrane
Genetic constraint (gnomAD): Loss-of-function variants: 27 observed, 123.93 expected, observed/expected ratio (o/e) 0.22, 90% interval 0.16 to 0.3. The upper end of that interval is the gene's LOEUF score, 0.3, which puts it in group 1 of 6, group 1 being the genes least tolerant of losing a copy. Missense variants: 1,808 observed, 1,851.2 expected, observed/expected ratio (o/e) 0.98, 90% interval 0.94 to 1.01. Synonymous variants: 790 observed, 767.76 expected, observed/expected ratio (o/e) 1.03, 90% interval 0.97 to 1.09.
Homologues: Orthologues: chimpanzee FGD5 (99% identical), macaque FGD5 (95% identical), dog FGD5 (80% identical), rabbit FGD5 (75% identical), pig FGD5 (74% identical), mouse Fgd5 (72% identical), rat Fgd5 (70% identical), guinea pig FGD5 (62% identical), tropical clawed frog fgd5 (45% identical), zebrafish fgd5a (41% identical), zebrafish fgd5b (14% identical), Caenorhabditis elegans exc-5 (12% identical), and 1 more. Paralogues in human: FGD6 (27% identical), FGD4 (13% identical), FARP2 (13% identical), FGD1 (13% identical), FARP1 (13% identical), FGD2 (13% identical), FGD3 (11% identical), ECT2L (8% identical), ARHGEF39 (6% identical), FRMD7 (5% identical).
Diseases named in the same sentence as FGD5 in open-access papers:
FGD5 is named in the same sentence as 18 diseases in open-access papers, as found by Europe PMC text mining. Sharing a sentence is not in itself a finding about the gene and the disease. The quoted sentences say what the papers report.
lung carcinoma (2 papers, 2014 to 2025). "Clarification of the role of FGD5 gene in renal and lung cancer progression is a goal for the nearest future." (PMID 24977159, 2014).
Tetralogy of Fallot (2 papers, 2020 to 2025). A congenital cardiac malformation comprising pulmonary stenosis, overriding aorta, ventricular septum defect, and right ventricular hypertrophy. "We also report novel plausible gene–disease associations for tetralogy of Fallot/pulmonary stenosis (CDC42BPA, FGD5), hypoplastic left or right heart (SMARCC1, TLN2, TRPM4, VASP), congenitally corrected transposition of the great arteries (UBXN10), and early-onset cardiomyopathy (TPCN1)." (PMID 32037394, 2020).
cervical cancer (1 paper, 2025). A primary or metastatic malignant neoplasm involving the cervix. "FGD5 is a proangiogenic gene associated with tumor progression, whose aberrant methylation has been detected in cervical cancer carcinogenesis." (PMID 39858027, 2025).
dysplasia (1 paper, 2020). A usually neoplastic transformation of the cell, associated with altered architectural tissue patterns. "In addition, Facio-Genital Dysplasia-5 (FGD5) is an important paralog of ARHGEF39 and it has been revealed that the FGD5 plays a role in VEGF-mediated angiogenesis and regulates the VEGF/PI3 kinase/Akt pathway." (PMID 33231603, 2020).
glucocorticoid deficiency (1 paper, 2025). "This study expands the TXNRD2 variant spectrum and highlights the importance of considering FGD5 in patients with isolated glucocorticoid deficiency, particularly those with ECG abnormalities." (PMID 40726908, 2025).
Hypertension (1 paper, 2020). The presence of chronic increased pressure in the systemic arterial system. "The Welcome Trust Case Control Consortium, using an intermediate approach between the genome-wide and candidate gene methods to analyze the link between hypertension and genes expressed in the endothelium, identified FGD5 as one of the possible loci." (PMID 32630286, 2020). "Moreover, in vitro studies using human cell lines have provided evidence for the involvement of FGD5 in the proangiogenic action of the endothelial growth factor, demonstrating the potential role of FGD5 in the development/progression of vasculature-related diseases, including hypertension." (PMID 32630286, 2020).
lymphoma (1 paper, 2024). A malignant (clonal) proliferation of B- lymphocytes or T- lymphocytes which involves the lymph nodes, bone marrow and/or extranodal sites. "Finally, complemental mouse models such as Fgd5-CreERT2, Vav1-Cre, CD19-Cre, or Mb1-Cre will be critical to determine which progenitor stage(s) are critical for lymphoma initiation by FBW7 deletion." (PMID 38485719, 2024).
Stroke (1 paper, 2017). Sudden impairment of blood flow to a part of the brain due to occlusion or rupture of an artery to the brain. "At 1 day after stroke, we detected, besides FGD5+(ZsGreen+)Tomato+ endothelial cells, also CD11b+Tomato+ZsGreen- MDMs." (PMID 28754163, 2017).
cancer (5 papers, 2014 to 2025). A tumor composed of atypical neoplastic, often pleomorphic cells that invade other tissues. "In order to further clarify the expression profile of FGD5 – AS1 in recurrent carcinoma, we explored the expression and prognosis of FGD5-AS1 through the GEPIA website based on The Cancer Genome Atlas (TCGA) database." (PMID 35475392, 2022). "Identified genes included well-known TSGs VHL, CTDSPL, LRRC3B, ALDH1L1, and EPHB1, but also genes not previously linked to cancer development (LRRN1, GORASP1, FGD5, and PLCL2)." (PMID 28326264, 2015). "Proteins encoded by a part of these genes are involved in signaling pathways and biological processes frequently affected in cancer, like apoptosis (GORASP1), regulation of actin cytoskeleton (FGD5), transmembrane signaling systems (GNAI2) or regulation of NFkappaB activity (NKIRAS1)." (PMID 28326264, 2015). "These genes include tumor suppressors or candidates (VHL, CTDSPL, LRRC3B, ALDH1L1, and EPHB1) and genes that were not previously considered as cancer-associated (e.g., LRRN1, GORASP1, FGD5, and PLCL2)." (PMID 24977159, 2014). "But there are also a number of genes which have not been previously reported as involved in cancer development, such as LRRN1, GORASP1, FGD5, and PLCL2." (PMID 24977159, 2014).
tumor (4 papers, 2014 to 2025). "Based on current research findings, the FGD5 protein may regulate vascular pruning by participating in the VEGF (vascular endothelial growth factor) signaling pathway and activating the CDC42 protein, thereby modulating neovascular networks in both physiological conditions and tumor tissues." (PMID 41199744, 2025).
FGD5 also shares sentences with these, for which no sentence is quoted: autism (1 paper); bladder cancer (1); cutaneous melanoma (1); hepatocellular carcinoma (1); leiomyosarcoma (1); prostate carcinoma (1); pulmonary stenosis (1); renal carcinoma (1).